SLC16A3 (solute carrier family 16 member 3)
Diseases named in the same sentence as SLC16A3 in open-access papers (continued):
Sharing a sentence is not in itself a finding about the gene and the disease.
tumor (continued). "Our findings suggested potential therapeutic strategies aimed at harnessing SLC16A3's impact on the tumour microenvironment to develop more effective treatment approaches for HCC patients and improve their prognosis." (PMID 39656344, 2024). "This prompted us to spotlight SLC16A3 for further analysis of its impact on tumour progression and treatment." (PMID 39656344, 2024). "Previous studies usually evaluated the expression of SLC16A3 in the entire cancer tissue and considered its role in the overall tumour environment." (PMID 39656344, 2024). "Upon SLC16A3 expression in macrophages, the transporter facilitates the export of lactate from cells, resulting in a decrease in tumour microenvironment pH." (PMID 39656344, 2024). "ALKBH5 can modulate Mct4/Slc16a3 expression and lactate content of the tumor microenvironment to regulate the composition of tumor‐infiltrating Treg and myeloid‐derived suppressor cells." (PMID 36260366, 2023). "Further research is needed to fully understand the mechanisms by which SLC16A3 contributes to tumor metabolism and the complex interactions within the tumor microenvironment." (PMID 37775731, 2023). "ALKBH5 modulates the sensitivity of the anti-PD-1 therapeutic response by regulating m6A abundance and RNA stability of Mct4/slc16a3 in the tumor microenvironment." (PMID 38102645, 2023). "By promoting lactate release, SLC16A3 contributes to tumor microenvironment acidification and serves as an energy source for adjacent cancer cells." (PMID 37775731, 2023). "A comprehensive analysis of DNA methylation data revealed that SLC16A3 has excellent predictive power for tumor diagnosis and prognosis." (PMID 34975331, 2022). "The results of the Wilcox test revealed that there was a significant correlation between the high expression of DBF4 (p<0.001), high expression of SLC16A3 (p<0.05), and tumor grade in HCC." (PMID 34975331, 2022). "PKM, ENO2, and SLC16A3 have been researched to have important effects on promoting tumor progression." (PMID 36245978, 2022). "In conclusion, we identified PTBP1and SLC39A1, and MMP9 and SLC16A3 as tumor specific antigens for LGG and GBM, respectively." (PMID 36307882, 2022). "We also demonstrated that the LCIIAR/hsa-miR184/SLC16A3/CDCP1 network regulates SLC16A3/CDCP1 overexpression in and is associated with poor prognosis in this tumour." (PMID 35860557, 2022). "SLC16A3, which encodes MCT4 (an important member of the solute transport family 16), is widely expressed in tumour cells, immune cells, and astrocytes and depends on glycolysis for energy metabolism." (PMID 36312898, 2022). "The results showed that AGL and SLC16A3 were significantly overexpressed in tumor samples compared to normal samples." (PMID 33991070, 2021). "Another study showed that ALKBH5 enhanced anti-PD-1 therapy response by regulating Mct4/Slc16a3 expression and lactate content and the composition of tumor-infiltrating Tregs and myeloid-derived suppressor cells in the tumor microenvironment." (PMID 34239358, 2021). "Survival and maintenance of the glycolytic phenotype of tumor cells is ensured by monocarboxylate transporter 4 (MCT4, encoded by the SLC16A3 gene) that efficiently transports L-lactate out of the cell." (PMID 33427197, 2021). "The mechanism was that ALKBH5 modulated Mct4/Slc16a3 expression, regulated lactate content of the tumor microenvironment, and adjusted the composition of tumor-infiltrating Treg cells and myeloid-derived suppressor cells." (PMID 34345203, 2021). "SLC16A3 overexpression partially rescued the tumor-suppressive effect of HIF1A knockdown in vivo." (PMID 41293164, 2025). "Available evidence indicates that SLC16A3, as a member of the monocarboxylate transporter family, promotes immune evasion and metastasis in various tumors by mediating lactate efflux to maintain tumor microenvironment acidification." (PMID 41583466, 2025).
tumor (continued). "On the other hand, recent studies indicate that SLC16A3 also participates in regulating ferroptosis: inhibiting its expression can reduce extracellular lactic acid accumulation, ameliorate the hypoxic tumor microenvironment, and induce ferroptosis in HCC by blocking ERK pathway activation." (PMID 41299729, 2025). "In addition, SLC16A3 expression in paired samples was much higher in most tumor types in comparison to healthy tissues." (PMID 40301866, 2025). "Given the metabolic role of SLC16A3 in maintaining redox homeostasis, its inhibition could sensitize tumor cells to ferroptosis under EGFR-TKI treatment." (PMID 41293164, 2025). "Thus, further investigation into the expression differences of SLC16A3 protein in tumor and normal tissues was considered necessary and was undertaken using the UALCAN and HPA databases." (PMID 40301866, 2025). "In parallel, qRT-PCR analysis validated the upregulated SLC16A3 mRNA levels in the tumor tissues." (PMID 41293164, 2025). "Earlier research has explored the crucial role of SLC16A3 overexpression in tumour progression." (PMID 39656344, 2024). "Pan-cancer, SLC16A3 and SLC16A8 are somatically mutated in less than 1% of tumours." (PMID 37999800, 2024). "SLC16A3 expression by pro‐tumour macrophages may be related to T‐cell dysfunction and tumour invasion." (PMID 39656344, 2024). "Collectively, these findings suggested that tumour‐promoting macrophage expression of SLC16A3 might lead to impaired T‐cell functionality, consequently contributing to the establishment of an immunosuppressive microenvironment." (PMID 39656344, 2024). "High glycolytic activity in tumor cells leads to increased lactate production, and the transport of lactate mediated by SLC16A3 contributes to an immunosuppressive microenvironment, reducing the efficacy of immune checkpoint inhibitors by impairing CD8+ T cell function." (PMID 39461979, 2024). "By inhibiting or modulating the activity of SLC16A3, it may be possible to disrupt lactate export, alter the tumor microenvironment, and potentially enhance the effectiveness of other cancer treatments." (PMID 37775731, 2023). "In melanoma and colon syngeneic mouse models, ALKBH5 attenuates tumor response to anti-PD-1 therapy by modulating Mct4/Slc16a3 expression, lactate content, as well as the composition of myeloid-derived suppressor cells and tumor-infiltrating Treg cells in the tumor microenvironment." (PMID 37612540, 2023). "SLC16A3 is known to play a significant role in tumor metabolism in the context of cancer." (PMID 37775731, 2023). "Likewise, a recent study found that knockout of Alkbh5 inhibited tumor growth during anti–PD-1 treatment by regulating Mct4/Slc16a3 expression, lactate content, and suppressive immune cell accumulation in TME." (PMID 36960074, 2023). "The most likely explanation for the tumor essentiality of transporter protein genes SLC16A3, SLC2A1, and SLC2A8 is that tumor cells have an increased demand for nutrients and this demand is met by enhanced cellular entry of nutrients through upregulation of specific transporters." (PMID 33427197, 2021). "Our results showed that HBx could increase H3K9me3 enrichment on genes of SHANK1 and SLC16A3, this might contribute to modulation of tumor-immune cell interactions." (PMID 27768594, 2016). "We found that the majority of genes co‐expressed with SLC16A1 were genes correlated with normal biological processes of cells, while genes co‐expressed with SLC16A3 were functionally clustered in the categories considered relevant for tumour progression and development." (PMID 25875424, 2015). "SLC16A3 encodes MCT4, a member of the solute carrier family 16, which transports lactate out of cells to prevent intracellular accumulation that would inhibit glycolysis, supporting the high glycolytic phenotype and invasiveness of tumor cells and maintaining an acidic TME." (PMID 40276602, 2025).
tumor (continued). "Hence, modulation of these immune factors could potentially explain a mechanism through which SLC16A3 contributes to tumour microenvironment suppression." (PMID 39656344, 2024). "Moreover, cross-analysis of the transcriptomic and the Circle-seq data revealed that two genes, SLC16A3 and BAIAP2L2, which were highly expressed in tumor tissues, were related to eccDNAs in the tumor sample and were associated with the survival rate in HCC patient cohorts." (PMID 38001569, 2023). "Moreover, previous studies demonstrated that ALKBH5 participates in regulating contents of metabolites (such as lactic acid) in the tumour microenvironment, similarly tumour infiltration of myeloid-derived suppressor cells (MDSCs)and T-regulatory cells (Tregs) through Mct4/Slc16a3." (PMID 34794452, 2021). "Both qRT-PCR and Western blot analyses revealed significant upregulation of SLC16A3 and downregulation of EGR2 in tumor tissues compared to adjacent normal tissues, which was corroborated by immunohistochemistry." (PMID 41583466, 2025). "We also excluded five markers that showed expression in both tumor subtypes (AGR2, SNAI2, KRT6A, MET, SLC16A3)." (PMID 39935174, 2025). "LAGs like SLC16A8, SLC16A1, and LDHB have a higher methylation ratio in tumor tissue than in normal tissue; a lower methylation ratio of SLC16A7 and SLC16A3 is noticed in that comparison." (PMID 37122693, 2023). "In particular, ALKBH5 modulates Mct4/Slc16a3 expression and lactate content in TME, so that the composition of tumor-infiltrating Tregs and MDSCs is altered." (PMID 35693795, 2022). "Mechanistically, ALKBH5 regulates the expression of Mct4/Slc16a3 and the content of lactate in the TME, thus suppressing the composition of tumor-infiltrating Treg cells as well as MDSCs, and finally regulating the response of PD-1 immunotherapy." (PMID 35254013, 2022). "Specifically, ALKBH5 regulates the expression level and lactic acid content of Mct4/Slc16a3 in the TME and the constitution of tumor infiltrating Tregs and myeloid-derived suppressor cells." (PMID 35069586, 2021). "The results showed that AGL, SLC16A3, and MIOX were significantly high expressed in tumor samples, whereas HKDC1 and ALDH7A1 were significantly low expressed in tumor samples." (PMID 33991070, 2021). "In harmony with this conclusion NOVA1, SLC16A3, SLC2A8, and TP73 were assigned to the essential category by De Kegel and Ryan, 2019 in less than 10% of the 558 tumor cell lines tested." (PMID 33427197, 2021). "Therefore, SLC16A3 expression could well reflect the activation status of tumor aerobic glycolysis." (PMID 34513685, 2021). "The mechanism is that ALKBH5 affects the efficacy of immunotherapy during immune checkpoint blockade by regulating the expression and lactate content of MCT4/Slc16a3 in TME and the composition of tumor-infiltrating T cells and myeloid suppressor cells." (PMID 34660577, 2021). "We identified four new types of tumor-specific chRNA; TRIM28-TRIM28, DHRS7B-TMEM11, PLXNB-BLRD1 and SLC16A3-METRNL, expressed in all AML groups." (PMID 29623188, 2017). "Using transgenic mouse models, we observed that SLC16A1 and SLC16A3 were both over‐expressed from normal mouse prostate to PIN lesions and medium and advanced PTEN‐null tumours." (PMID 25875424, 2015). "Similar to observations in spheroids, ERβ expression was maintained and SLC16A3 and CD147 gene expression were down-modulated in tumor samples recovered from KB9520 treated mice." (PMID 26208479, 2015). "By RT-PCR of tumor samples, we documented that KB9520 treatment decreased the expression of the SLC16A3 and CD147 genes and increased the expression of the CDH1 gene." (PMID 26208479, 2015). "For example, ALKBH5-mediated changes in m6A modification may regulate the expression of Mct4/Slc16a3 and lactate content in the CRC microenvironment, as well as the composition of tumor-infiltrating Treg and myeloid-derived suppressor cells." (PMID 40958857, 2025).
tumor (continued). "Its target specificity and in vivo efficacy have been further supported by multiple independent studies, in which MSC-4381 effectively blocked SLC16A3-mediated lactate oxidation and suppressed tumor progression without detectable off-target effects." (PMID 41293164, 2025). "Similarly, the m6A demethylase Alkbh5 modulates Mct4/Slc16a3 expression and lactate levels in the TME, enhancing the efficacy of cancer immunotherapy by altering the composition of tumor-infiltrating Tregs and MDSCs." (PMID 39766353, 2024). "It has also been demonstrated that by regulating SLC16A3 in tumor cells, the TME's lactate levels can be reduced, leading to a decreased infiltration of inhibitory immune cells, and ultimately enhancing the sensitivity of tumor patients to immunotherapy." (PMID 38779008, 2024). "In addition, SLC16A3 might be associated with decreased CD8+ T‐cell infiltration and increased myeloid‐derived suppressor cells (MDSC) enrichment, indicating that targeting SLC16A3 may reverse the suppressive tumour microenvironment and enhance the efficacy of anti‐PD‐1 therapy." (PMID 39656344, 2024). "Furthermore, two genes, SLC16A3 and BAIAP2L2, with a higher transcription level in tumor tissues, were related to eccDNAs exclusively detected in three HCC samples and were negatively associated with survival rates in HCC cohorts from public databases." (PMID 38001569, 2023). "And the mRNA expression of MMP9 and SLC16A3 was significantly negative related to tumor purity (PTBP1, r = − 0.53; SLC39A1: r = − 0.58; P < 0.05)." (PMID 36307882, 2022). "For instance, ALKBH5 regulated Tregs and MDSC accumulation via modulating the expression of Mct4/Slc16a3; FTO facilitated immune invasion and desensitized tumor cells to T cell cytotoxicity; YTHDF1 was correlated with immune cell infiltration but attenuated DCs' cross-presentation capacity." (PMID 35936362, 2022). "The reduced activation of AKT, along with the reduction in expression of SLC16A3 and CD147, could be the explanation for the reduced tumor growth." (PMID 26208479, 2015). "SLC16A3 was strongly regulated in tumour cell lines and HUVE cells in vitro and although signal was low in tumours it was upregulated more than two-fold in seven tumours." (PMID 16052224, 2005). "Representative IHC images from the HPA database showed elevated SLC16A3 expression in LUAD tissues compared to that in normal lung tissues, with IHC validation in our clinical LUAD cohort, further confirming enhanced SLC16A3 expression in tumor tissues compared to that in matched normal samples." (PMID 41293164, 2025). "We demonstrated that EGFRHIGH tumor subcluster was distinctly elevated in the pembrolizumab-treated group and exhibited significantly higher level of lactate producing biomarkers including LDHA and SLC16A3 compared to the combination group in both HNSCC and LUSC PDX." (PMID 38916448, 2024). "SLC16A3 levels in tumor vs. metastatic tissues showed non-significant changes." (PMID 37934721, 2023). "Indeed, these tumours are unable to use aerobic glycolysis and consistently, show a decreased expression of HIF1α and several other elements of glycolysis such as SLC2A1, PDK1, LDHA, and SLC16A3." (PMID 34932167, 2021). "Detection of the tumour GZMB marker by flow cytometry and immunohistochemistry methods, respectively, showed a significant upregulation of GZMB expression in the MCT4i group, indicating that inhibiting SLC16A3 could effectively enhance the cytotoxic ability of immune cells." (PMID 39656344, 2024). "Interestingly, in silico analysis of MCT4/SLC16A3 and HIF-1α/HIF1A expression in microdissected GBM tumor compartments obtained from the IVY Glioblastoma Atlas Project database revealed an expression gradient for both genes from the leading edge towards the tumor center in most tumor specimens." (PMID 33936203, 2021).
tumor (continued). "Meanwhile, MMP9 and SLC16A3, the negative prognostic factors overexpressed in GBM, were identified as tumor-specific antigens for GBM patients." (PMID 36307882, 2022). "Moreover, PCBP1-AS1 also showed a significant negative correlation with FAM3C, BCL10, SLC16A3, WDR1, and other key molecules of tumor malignant behavior." (PMID 38433921, 2024). "Among most of these tumor types, a negative correlation between gene methylation and mRNA expression was revealed by calculating the Spearman correlation, including HIF1A, SLC16A1, UEVLD, SLC16A8, PFKFB2, LDHB, and SLC16A3." (PMID 37122693, 2023).